RABAC1 (Rab acceptor 1)
Description:
General Rab protein regulator required for vesicle formation from the Golgi complex. May control vesicle docking and fusion by mediating the action of Rab GTPases to the SNARE complexes. In addition it inhibits the removal of Rab GTPases from the membrane by GDI.
Synonyms: PRA1; PRAF1; YIP3
Tractability: Antibody: UniProt places it where antibodies can reach, with medium confidence; UniProt predicts a signal peptide or a membrane-spanning region; its Gene Ontology location is reachable by antibodies, with medium confidence. PROTAC: ubiquitination databases record sites on it; its protein half-life has been measured.
Gene: Protein-coding gene on chromosome 19 (41,956,681 to 41,959,370, reverse strand). Ensembl gene ENSG00000105404.
Subcellular location: Cell membrane; Cytoplasm; Golgi apparatus; Cytoplasmic vesicle, secretory vesicle, synaptic vesicle
Gene Ontology:
Molecular function: identical protein binding; protein binding; GTPase binding; proline-rich region binding
Cellular component: membrane; cytoplasm; Golgi apparatus; plasma membrane; glutamatergic synapse; presynapse; synapse; synaptic vesicle
Genetic constraint (gnomAD): Loss-of-function variants: 16 observed, 22.53 expected, observed/expected ratio (o/e) 0.71, 90% interval 0.48 to 1.08. The synonymous counts are far from expectation, so gnomAD's model fits this gene poorly and the ratio says little. Missense variants: 227 observed, 248.35 expected, observed/expected ratio (o/e) 0.91, 90% interval 0.82 to 1.02. Synonymous variants: 139 observed, 109.87 expected, observed/expected ratio (o/e) 1.27, 90% interval 1.1 to 1.46.
Homologues: Orthologues: chimpanzee RABAC1 (99% identical), macaque RABAC1 (98% identical), guinea pig RABAC1 (96% identical), dog RABAC1 (95% identical), rat Rabac1 (95% identical), mouse Rabac1 (95% identical), rabbit RABAC1 (93% identical), tropical clawed frog rabac1 (68% identical), zebrafish rabac1 (61% identical), pig RABAC1 (56% identical), Drosophila melanogaster CG1418 (34% identical).
Diseases named in the same sentence as RABAC1 in open-access papers:
RABAC1 is named in the same sentence as 20 diseases in open-access papers, as found by Europe PMC text mining. Sharing a sentence is not in itself a finding about the gene and the disease. The quoted sentences say what the papers report.
breast carcinoma (1 paper, 2019). "Interestingly, it predicted positive association in breast cancer through co-relation with MYL6, RABAC1 and other genes, while negatively regulating ATL2, ICE2 and TADA1 in melanoma and HCC." (PMID 30857225, 2019).
lung carcinoma (1 paper, 2014). "Notably, EGLN2 and RABAC1 together form part of a 4-gene signature of invasive lung cancer." (PMID 24498427, 2014).
cancer (1 paper, 2025). A tumor composed of atypical neoplastic, often pleomorphic cells that invade other tissues. "In addition, the proportion of the APH1A-203 and RABAC1-201 isoforms, which were upregulated in our data, exhibited a progressive increase across cancer stages in the TCGA cohort." (PMID 40702779, 2025).
tumor (1 paper, 2012). "The overexpression of MICAL1 and RABAC1 is likely due to the presence of stromal cells in the tumor as MICAL1 is highly expressed in different types of hematopoietic cells (dendritic cells, mast cells and NK cells) and RABAC1 in mast cells (data not shown)." (PMID 22724020, 2012).
RABAC1 also shares sentences with these, for which no sentence is quoted: infection (14 papers); Candida infection (2); fungal infection (2); atrial fibrillation (1); B cell lymphoma (1); bacterial infections (1); bladder cancer (1); blastomycosis (1); Lyme borreliosis (1); melanoma (1); nasopharyngeal carcinoma (1); Respiratory tract infection (1); retinitis pigmentosa (1); vaginal candidiasis (1); vaginal infections (1); Zinc deficiency (1).